INS (insulin)
Diseases named in the same sentence as INS in open-access papers (continued):
Sharing a sentence is not in itself a finding about the gene and the disease.
Insulin resistance (continued). "For these reasons, there is currently active research into natural substances with mechanisms similar to those of drug formulations that may exhibit activities such as regulating insulin secretion, improving insulin resistance, and enhancing insulin sensitivity, with fewer side effects." (PMID 39815341, 2025). "In addition, high levels of uric acid may interfere with the insulin signaling pathway, further exacerbating insulin resistance." (PMID 40092731, 2025). "Therefore, the present study aimed to investigate the potential benefits of asparagus supplementation on blood glucose, insulin, homeostasis model assessment of insulin resistance (HOMA-IR) and β-cell function (HOMA-B), lipid profile, and oxidative stress in overweight and obese individuals." (PMID 41157258, 2025). "Additionally, experimental studies have suggested that the hepatitis B X protein (HBx) may play a role in the development of insulin resistance by interfering with the hepatic insulin signaling pathway." (PMID 39898253, 2025). "In rodents, miR-33 deletion can cause weight gain and insulin resistance irrespective of normal chow or high-fat diet feeding, indicating that its agonism could be good target in maintaining insulin sensitivity even in cases of HFD." (PMID 40696355, 2025). "Unmeasured confounders (e.g., cortisol, glucagon, insulin) or residual thyroid-independent effects may contribute, though our adjustments for metabolic proxies (which correlate with insulin resistance and hormonal dysregulation) e.g. obesity, lipids, and thyroid autoimmunity, mitigate some concerns." (PMID 40600010, 2025). "Furthermore, the high concentration of insulin, which may simulate insulin resistance, can lead to the elevated apoptosis of ovarian granulosa cells in PCOS." (PMID 39871124, 2025). "Therefore, the following comparisons of all relevant variables between the groups/subgroups were corrected for differences in age, pre-pregnancy BMI, gestational age at sampling, fasting insulin, fasting glucose, and homeostatic model assessment of insulin resistance (HOMA-IR)." (PMID 39984726, 2025). "Our findings suggest that isotretinoin reduces the abundance of specific triglycerides, such as TG (15:0_17:0_18:0), TG (17:0_18:0_18:0), and TG (18:0_18:0_18:0), which are enriched in the insulin resistance pathway and may contribute to improved insulin sensitivity." (PMID 40860874, 2025). "Since elevated insulin is a prevalent feature of PCOS that worsens hyperandrogenism and hypothalamic–pituitary–ovarian dysfunction, it is critical to investigate all of its potential causes, instead of presuming it is the consequence of peripheral insulin resistance." (PMID 40013621, 2025). "In addition, several biological pathways including AMPK signaling, FoxO signaling, insulin signaling, adipocytokine signaling, diabetic cardiomyopathy, and insulin resistance where GLUT4 plays a role may get affected by altered GLUT4 expression and function." (PMID 40854653, 2025). "Furthermore, the observation of normal or low glucose levels alongside high insulin levels in testosterone-treated rats suggests that elevated androgens may contribute to insulin resistance in this experimental PCOS model." (PMID 41463090, 2025). "Moreover, low-grade inflammation promotes insulin resistance, and this may lead to cognitive decline via impaired insulin signaling." (PMID 40719824, 2025). "Considering that the MAMs contains various proteins integral to insulin signaling and that its structural integrity is essential for the proper function of insulin, it is not unexpected that abnormal structure and functions in MAMs are observed in the context of insulin resistance and DM." (PMID 40661148, 2025). "Additionally, increased acylcarnitine concentrations have been observed in obese individuals; their accumulation may disrupt insulin signaling and contribute to the development of insulin resistance." (PMID 40422879, 2025).
Insulin resistance (continued). "However, with HOMA-IR as the surrogate marker, FPG in addition to insulin and total cholesterol levels associated with insulin resistance in participants without past COVID-19 status." (PMID 40273152, 2025). "Finally, our data were primarily collected from mice, but the known relationships of miR-30a expression in adipocytes and whole-body insulin sensitivity in people justify future studies to examine if any targets of miR-30a influence WAT fibrosis and cause insulin resistance in obesity." (PMID 40471675, 2025). "Additionally, progressive changes in insulin signaling, or “insulin resistance,” can be exacerbated by chronic inflammation, oxidative stress, and lipid accumulation, which, when paired, complicate the molecular dysregulation underpinning the progression of T2DM." (PMID 40786421, 2025). "Therefore, the upregulation of IL-6 during obesity may represent an adaptive mechanism aimed at enhancing insulin production and ameliorating glucose tolerance to counteract obesity-related insulin resistance." (PMID 40519917, 2025). "However, elevated liver GPx, alongside fat accumulation, may contribute to insulin resistance, as ROS can positively regulate insulin signaling in HF‐fed animals." (PMID 40926357, 2025). "Furthermore, despite skeletal muscle accounting for 80% of insulin-stimulated glucose disposal, and being the primary site of insulin resistance in individuals with type 2 diabetes, current therapies do not directly target muscle glucose disposal for therapeutic gain." (PMID 40156616, 2025). "Thus, excessive PTEN expression impairs insulin signaling and contributes to insulin resistance." (PMID 41459066, 2025). "The correlation between insulin resistance and AD’s pathology underscores the possibility that metabolic dysfunction may intensify neurodegenerative processes, indicating that modulating insulin signalling might provide therapeutic strategies for mitigating AD development." (PMID 39932549, 2025). "Furthermore, substantial improvements were observed across multiple metabolic parameters: fasting blood sugar, triglycerides, total cholesterol, homeostasis model assessment of insulin resistance, and quantitative insulin sensitivity check index (all p < 0.05)." (PMID 41277972, 2025). "Furthermore, dysfunctional adipocytes caused by obesity have impaired storage capabilities, promoting the release of FFA into circulation and ectopic fat accumulation which interfere with insulin signaling pathways and contribute to systemic insulin resistance and eventual T2D." (PMID 41180177, 2025). "The combination of insulin resistance and deficiency observed in CIRDD and SIDRD may be influenced by the genetic characteristics of the Asian ethnicity, with a lower capacity for insulin secretion and increased insulin resistance compared to Western populations." (PMID 41255523, 2025). "Research has shown that in patients with metabolic syndrome, primarily exhibiting insulin resistance, increased circulating insulin levels may lead to enhanced synthesis and uptake of fatty acids by hepatic lipogenic cells, exacerbating triglyceride accumulation in the liver." (PMID 40084133, 2025). "Cerebral insulin resistance results in disinhibition of glycogen synthase kinase-3β (GSK-3β) that promotes tau hyperphosphorylation and amyloidogenic processing of the amyloid precursor protein (APP); thus, disrupted insulin signaling is linked to the classical AD pathologies." (PMID 41226821, 2025). "VLDL may also influence NAFLD through its impact on insulin resistance or by affecting oxidative stress, as evidenced by research showing that VLDL uptake and lipid deposition are associated with increased oxidative stress and diminished insulin sensitivity." (PMID 41031052, 2025).
Insulin resistance (continued). "It is inexplicable how insulin resistance in subjects with normal glucose tolerance could be responsible for increased insulin secretion when blood glucose concentrations are still normal and this is another argument against a primary role for insulin resistance-mediated hyperinsulinemia." (PMID 41009753, 2025). "Additionally, insulin resistance has been shown to develop in primary cultured myotubes when exposed to a combination of long- and medium-chain acylcarnitines and insulin-stimulated glucose uptake is compromised in 3T3-L1 adipocytes incubated with 0.1 mM decanoyl-l-carnitine." (PMID 40892466, 2025). "Furthermore, SFAs can directly impair insulin signaling and exacerbate systemic insulin resistance." (PMID 40647314, 2025). "Given the well-established interaction between obesity and hypertension under insulin-resistant conditions, these findings may help explain why the composite indices incorporating both insulin resistance and visceral adiposity (TyG-CVAI and TyG-BRI) demonstrated superior predictive capability." (PMID 41457293, 2025). "Insulin Resistance (IR): Also referred to as “insulin insensitivity”, is primarily defined by a diminished ability of peripheral tissues to uptake and utilize glucose, particularly skeletal muscle, fat tissue, and the liver, resulting in an impaired response to insulin." (PMID 41585795, 2025). "In addition to contributing to β-cell dysfunction, mtDNA DAMPs may impair insulin signaling and promote insulin resistance, as shown in skeletal muscle via TLR9-mediated pathways." (PMID 41156500, 2025). "While insulin resistance appears to be the primary driver, elevated uric acid may also contribute to worsening IR by inducing endothelial dysfunction, oxidative stress, and impaired insulin signaling in adipose tissue." (PMID 40943711, 2025). "The link between obesity, inflammation, and insulin resistance was first discovered when it was observed that the adipose tissue of obese individuals emitted increased levels of pro-inflammatory cytokines, and that antagonism led to increased insulin sensitivity." (PMID 41302116, 2025). "Furthermore, pancreatic islet cells isolated from these Pb-treated rats exhibited reduced cell viability and impaired glucose-stimulated insulin secretion (GSIS), which was associated with increased ROS levels and elevated glycogen synthase kinase-3 beta (GSK-3β), contributing to insulin resistance." (PMID 40408591, 2025). "The increased leptin resistance associated with high levels of free fatty acid and inflammatory cytokines may contribute to the reduction in lipid oxidation in insulin-sensitive organs, leading to the accumulation of lipids (lipotoxicity) and insulin resistance." (PMID 40137085, 2025). "Insulin resistance (IR) is characterized by a condition where target cells do not respond adequately to normal insulin levels, resulting in negative feedback causing excessive insulin secretion." (PMID 40009162, 2025). "Moreover, elevated ROS levels may activate serine/threonine kinases (e.g., PKC, AKT, mTOR, GSK-3, p38 MAPK), promoting serine phosphorylation of IRS proteins and impairing insulin signaling, thereby facilitating insulin resistance." (PMID 40453670, 2025). "Finally, interventions targeting IDE must be implemented with caution, as any disruption of insulin clearance could lead to exacerbations in hyperinsulinemia and worsen insulin resistance." (PMID 40724942, 2025). "For instance, elevated C16:0 and C18:0 ceramides correlate with insulin resistance and β-cell dysfunction in Type 2 Diabetes, whereas, exercise selectively reduces C16:0 and enriches very-long-chain ceramides (C24:0, C24:1), enhancing insulin sensitivity and mitochondrial capacity." (PMID 41385585, 2025). "However, in the context of established DM with significant insulin resistance, the incretin effect may be attenuated due to impaired insulin signaling or reduced GLP-1R responsiveness." (PMID 40732345, 2025).
Insulin resistance (continued). "The higher phosphorus value in the HHS group may be explained by a longer onset of disease and a prolonged timeframe without insulin or underlying insulin resistance or by underlying kidney disease and poor GFR." (PMID 40880442, 2025). "Central obesity may decrease insulin's ability to uptake glucose, leading to insulin resistance." (PMID 40548446, 2025). "Interestingly, exposing primary female subcutaneous adipocytes to insulin in vitro significantly increases AKR1C3 mRNA expression, which points to the potential for elevated insulin to potentiate this rise in intra-adipose androgens and subsequent insulin resistance." (PMID 40013621, 2025). "Similarly, it has been evidenced that glucocorticoids and insulin enhance the consumption of fatty foods, which allows us to suppose that the combination of high insulin and cortisol levels can be a powerful inducer of obesity and insulin resistance." (PMID 40276070, 2025). "Intramuscular adipose tissue infiltration (myosteatosis) may contribute to disease progression through the local secretion of inflammatory adipokines from adipocytes, which induce insulin resistance, impairs insulin diffusion capacity, and weakens immune defenses." (PMID 41149507, 2025). "Hypothetically, diminished LPL activity regarding T2D could augment circulating triglyceride concentrations and increase lipotoxicity, characterized by the adverse impact of excess fatty acids on insulin signaling and glucose homeostasis and worsening insulin resistance." (PMID 41373652, 2025). "Furthermore, the diminished prevalence of saturated fatty acids, advanced glycation products, nitrosamines, and heme iron—all of which are linked to insulin resistance and lipotoxicity—can assist in the prevention of insulin resistance and the promotion of insulin sensitivity." (PMID 40697264, 2025). "However, corticosteroids also have significant diabetogenic effects, contributing to NODAT development by increasing peripheral insulin resistance, reducing insulin secretion from the pancreas, stimulating gluconeogenesis in the liver, and promoting pancreatic beta-cell apoptosis at high doses." (PMID 39941214, 2025). "Moreover, obese children often experience insulin resistance, leading to elevated insulin levels, which may further disrupt hormone balance." (PMID 41393281, 2025). "However, dorzagliatin’s mechanism of action, which enhances glucose-stimulated insulin secretion and GLP-1 release while improving β-cell function and reducing insulin resistance in type 2 diabetes patients, may mitigate the risk of severe hypoglycemia." (PMID 40573322, 2025). "The insulin subgroup may promote lipodystrophy/insulin resistance." (PMID 40166930, 2025). "Additionally, impaired insulin secretion and intensified insulin resistance may contribute to this phenomenon." (PMID 40104135, 2025). "Furthermore, these agents reduce insulin resistance and enhance peripheral insulin sensitivity." (PMID 40093018, 2025). "Indeed, several studies reveal that the changes in maternal lipid metabolism are closely related the role of hormones and onset of insulin resistance during gestation, and increased levels of estrogen, progestrogen, and insulin facilitate lipid production and storage during early pregnancy." (PMID 41356011, 2025). "Somewhat surprisingly and contrary to our hypothesis, GG supplementation did not improve the HFD + STZ-induced negative impacts on glucose homeostasis (i.e., glucose intolerance, insulin resistance, low pancreatic insulin expression) and bone microstructure of trabecular and cortical bones." (PMID 41465559, 2025). "However, in the context of chronic high-fructose intake, its potent lipogenic capacity induces lipotoxicity, which impairs the insulin-Akt1 signaling pathway and leads to insulin resistance, thereby shifting the primary regulation of DNL to alternative pathways such as ChREBP." (PMID 41415834, 2025).
Insulin resistance (continued). "If these sugar intakes are sufficient to cause insulin resistance and subsequent negative health outcomes, genes that help regulate insulin sensitivity and production may be selected for." (PMID 39786569, 2025). "Additionally, increased downstream phosphorylation of phosphatidylinositol-3 kinase (PI3K), AKT, and glucose transporter-4 (GLUT4) during GDM pregnancies may intensify insulin resistance due to impaired insulin signaling." (PMID 40362828, 2025). "Moreover, the MCD diet model, while useful in inducing liver injury and inflammation, leads to metabolic alterations such as weight loss and decreased insulin levels that contrast starkly with human MASH, which is typically associated with obesity and insulin resistance." (PMID 40893881, 2025). "Moreover, the reduction in systemic low-grade inflammation and positive microbiome regulation may also lead to improvements in insulin sensitivity and insulin resistance, both hallmarks of T2DM." (PMID 39940436, 2025). "PTP 1B inhibitors may help reduce insulin resistance and return insulin and plasma glucose levels to normal without causing hypoglycemia." (PMID 39940428, 2025). "Insulin resistance refers to a pathological state in which the sensitivity and responsiveness of target tissues—primarily skeletal muscle, liver, and adipose tissue—are reduced, leading to a decreased efficiency of insulin-mediated glucose uptake and utilization." (PMID 41018201, 2025). "GLP-1RA are associated with significant weight loss and reduction of insulin resistance, as GLP-1 increases expression of glucose transporters and modulation of lipid metabolism, and in conjunction with its anti-inflammatory activity, leads to improvement in insulin sensitivity." (PMID 40919598, 2025). "Insulin resistance generally results from the combined impairment of insulin sensitivity (ie, the shift of the insulin concentration–effect curve to higher insulin concentrations), and of insulin responsiveness (ie, the reduction of the maximal effect of insulin in its target tissues)." (PMID 39998445, 2025). "However, after resection, GH level normalization and the decrease in insulin resistance may make patients prone to hypoglycemia, especially if an insulin infusion was being used previously during the case." (PMID 40385738, 2025). "Interestingly, within the same adipose tissue depot, all genes exhibit a tendency for lower gene expression among individuals with insulin resistance compared to insulin sensitive subjects, which may hint at a potential role in insulin metabolism." (PMID 41275133, 2025). "Thus, we surmise that the obese individuals are more likely to suffer from overload of fatty acids via intake of various fatty acid which may induce hepatic insulin resistance and impaired insulin clearance." (PMID 40672429, 2025). "Underlying T2DM, inflammation, oxidative stress, and impaired insulin production and secretion among insulin resistance have been extensively studied, along with the identification of potential biomarkers that may assist in future treatment and prognostic strategies." (PMID 41109135, 2025). "Additionally, studies should investigate individuals who have already experienced a stroke, monitoring their glucose and insulin levels to assess whether prediabetes or insulin resistance contributed to the stroke." (PMID 41296388, 2025). "However, it is important to note that physiological insulin resistance is expected during puberty, and measuring insulin levels could introduce confounding bias." (PMID 40487022, 2025). "Additionally, the intake of AX can improve chronic glycemic control by enhancing insulin sensitivity and reducing insulin resistance, which ultimately promotes glucose uptake into peripheral tissues (muscle and adipose) and suppresses hepatic glucose production." (PMID 40944228, 2025).